GCSAM (germinal center associated signaling and motility)
Description:
Involved in the negative regulation of lymphocyte motility. It mediates the migration-inhibitory effects of IL6. Serves as a positive regulator of the RhoA signaling pathway. Enhancement of RhoA activation results in inhibition of lymphocyte and lymphoma cell motility by activation of its downstream effector ROCK. Is a regulator of B-cell receptor signaling, that acts through SYK kinase activation.
Synonyms: hGAL; GCET2; MGC40441; GCAT2
Tractability: Antibody: UniProt places it where antibodies can reach, with high confidence; its Gene Ontology location is reachable by antibodies, with medium confidence. PROTAC: UniProt records ubiquitination sites on it; ubiquitination databases record sites on it.
Gene: Protein-coding gene on chromosome 3 (112,120,839 to 112,133,270, reverse strand). Ensembl gene ENSG00000174500.
Subcellular location: Cytoplasm; Cell membrane
Gene Ontology:
Molecular function: actin binding; myosin II binding; protein binding; protein kinase binding
Biological process: negative regulation of lymphocyte migration; regulation of B cell receptor signaling pathway; regulation of lymphocyte migration
Cellular component: plasma membrane; cytoplasm
Genetic constraint (gnomAD): Loss-of-function variants: 5 observed, 8.92 expected, observed/expected ratio (o/e) 0.56, 90% interval 0.29 to 1.18. That is too few expected variants to judge how well the gene tolerates losing a copy. Missense variants: 148 observed, 173.23 expected, observed/expected ratio (o/e) 0.85, 90% interval 0.75 to 0.98. Synonymous variants: 52 observed, 58.84 expected, observed/expected ratio (o/e) 0.88, 90% interval 0.71 to 1.11.
Homologues: Orthologues: chimpanzee GCSAM (97% identical), macaque GCSAM (93% identical), pig GCSAM (67% identical), rabbit GCSAM (67% identical), dog GCSAM (58% identical), mouse Gcsam (56% identical), rat Gcsam (56% identical), guinea pig GCSAM (51% identical). Paralogues in human: GCSAML (26% identical).
Diseases named in the same sentence as GCSAM in open-access papers:
GCSAM is named in the same sentence as 17 diseases in open-access papers, as found by Europe PMC text mining. Sharing a sentence is not in itself a finding about the gene and the disease. The quoted sentences say what the papers report.
lymphoma (13 papers, 2011 to 2026). A malignant (clonal) proliferation of B- lymphocytes or T- lymphocytes which involves the lymph nodes, bone marrow and/or extranodal sites. "Immunoblot analysis of tumor extracts confirmed that cellular proteins that are highly expressed in GC B cells, including cyclin D3, GCSAM, TCL1, Myb, TCF3 and BACH2 are expressed at higher levels in the ΔEBNA2 + Myc lymphomas in comparison to the ΔEBNA2 alone lymphomas." (PMID 38620028, 2024). "Of note, the P493-6 cell line expresses much lower levels of some BL-associated (and GC B cell expressed) cellular proteins in comparison to the N1, N3 and N4 stable cell lines derived from the ΔEBNA2 + Myc lymphomas, including CD10, GCSAM, BACH2, and CD179B (IGLL1)." (PMID 38620028, 2024).
cancer (1 paper, 2016). A tumor composed of atypical neoplastic, often pleomorphic cells that invade other tissues. "With regard to B cells, changes included decreases in the gene expression of CD19, CD22, CD72, IKZF3 and GCSAM in cancer patients compared to healthy donors." (PMID 28936253, 2016).
GCSAM also shares sentences with these, for which no sentence is quoted: diffuse large B-cell lymphoma (5 papers); B-cell lymphoma (3); Burkitt lymphoma (2); Hodgkins lymphoma (2); tumor (2); AA amyloidosis (1); autoimmune disease (1); B-cell neoplasm (1); follicular lymphoma (1); mantle cell lymphoma (1); marginal zone lymphoma (1); non-small cell lung carcinoma (1); ovarian carcinoma (1); plasma cell neoplasm (1); urticaria (1).